FCGR3B (Fc gamma receptor IIIb)
Description:
Receptor for the Fc region of immunoglobulins gamma. Low affinity receptor. Binds complexed or aggregated IgG and also monomeric IgG. Contrary to III-A, is not capable to mediate antibody-dependent cytotoxicity and phagocytosis. May serve as a trap for immune complexes in the peripheral circulation which does not activate neutrophils.
Synonyms: CD16-I; FcRIIIb; CD16b; FCG3; FCGR3; HNA-1; CD16; FcgammaRIIIb
Tractability: Small molecule: a structure with a bound ligand is known. Antibody: UniProt places it where antibodies can reach, with high confidence; its Gene Ontology location is reachable by antibodies, with high confidence; UniProt predicts a signal peptide or a membrane-spanning region.
Target class: Membrane receptor
Gene: Protein-coding gene on chromosome 1 (161,623,196 to 161,631,963, reverse strand). Ensembl gene ENSG00000162747.
Subcellular location: Cell membrane; Secreted
Pathways (Reactome):
Immune System: Neutrophil degranulation
Metabolism of proteins: Post-translational modification: synthesis of GPI-anchored proteins
Gene Ontology:
Molecular function: GPI anchor binding; IgG receptor activity
Biological process: antibody-dependent cellular cytotoxicity; cell surface receptor signaling pathway; immune response; Fc-gamma receptor signaling pathway
Cellular component: extracellular exosome; plasma membrane; external side of plasma membrane; extracellular region; secretory granule membrane
Genetic constraint (gnomAD): Loss-of-function variants: 20 observed, 19.81 expected, observed/expected ratio (o/e) 1.01, 90% interval 0.71 to 1.47. The upper end of that interval is the gene's LOEUF score, 1.47, which puts it in group 6 of 6, group 1 being the genes least tolerant of losing a copy. Missense variants: 190 observed, 236.47 expected, observed/expected ratio (o/e) 0.8, 90% interval 0.71 to 0.91. Synonymous variants: 79 observed, 88.74 expected, observed/expected ratio (o/e) 0.89, 90% interval 0.74 to 1.07.
Homologues: Orthologues: macaque FCGR3 (91% identical), rabbit FCGR3A (62% identical), rabbit FCGR3B (62% identical), mouse Fcgr4 (61% identical), rat Fcgr3a (59% identical). Paralogues in human: FCGR3A (97% identical), FCGR2A (45% identical), FCGR2B (42% identical), FCGR2C (42% identical), FCGR1A (40% identical), FCER1A (37% identical), FCRL5 (32% identical), FCRLB (32% identical), FCRL3 (25% identical), FCRL4 (25% identical), FCRLA (22% identical), PECAM1 (21% identical), and 5 more.
Diseases named in the same sentence as FCGR3B in open-access papers:
FCGR3B is named in the same sentence as 93 diseases in open-access papers, as found by Europe PMC text mining. Sharing a sentence is not in itself a finding about the gene and the disease. The quoted sentences say what the papers report.
systemic lupus erythematosus (25 papers, 2010 to 2025). An autoimmune multi-organ disease typically associated with vasculopathy and autoantibody production. "For example, in the human population, alterations in the number of copies of the CCL3L1 gene have been found to be linked with susceptibility to HIV-1/AIDS and FCGR3B copy number variation has a significant effect on systemic lupus erythematosus (SLE)." (PMID 39409846, 2024). "A low copy number (<2) of FCGR3B has been implicated in multiple autoimmune diseases, including systemic lupus erythematosus (SLE), Sjogren’s syndrome, and RA." (PMID 36553504, 2022). "On the other hand, a low FCGR3B copy number is associated with auto-immune diseases such as systemic lupus erythematosus (SLE), MPA, and GPA." (PMID 33679731, 2021). "Deletions of FCGR3B have been suggested to increase the risk of inflammatory diseases such as systemic lupus erythematosus and rheumatoid arthritis (RA)." (PMID 27995740, 2017). "These include multiple examples of CNVs associated with cancer susceptibility, the association of the FCGR3B gene copy number variant with systemic lupus erythematosus (SLE), and CCL3L1 gene copy number, which has been linked to HIV susceptibility." (PMID 27277319, 2016). "An association between low FCGR3B CN and LN has been observed in Caucasian patients as well as in experimental lupus, but several studies have been unable to replicate these associations in Asian or Afro-American patients." (PMID 23864940, 2013). "Further, multiple studies have identified low FCGR3B CN (i.e., <2 copies) as a risk factor for systemic autoimmune diseases, such as systemic lupus erythematosus, rheumatoid arthritis, and primary Sjögren's syndrome." (PMID 22701122, 2012). "Numerous previous studies have suggested that FCGR3B may be a risk factor for a range of autoimmune diseases, such as systemic lupus erythematosus and rheumatoid arthritis.The exact rationale for the role of FCGR3B in the treatment of CC is unclear." (PMID 38532933, 2024). "Low copy number of FCGR3B had been identified to be associated with a number of systemic autoimmune diseases, such as systemic lupus erythematosus (SLE), rheumatoid arthritis (RA), ANCA-associated vasculitis (AAV), and anti-glomerular basement (anti-GBM disease) disease." (PMID 28083015, 2016). "Similarly, for the FCGR3B gene that is associated with systemic lupus erythematosus (SLE) and rheumatoid arthritis, multiple breakpoints of deletions lie in a 24.5-kb region." (PMID 27695476, 2016). "Notably, variations in the FCGR3B gene have been closely linked to the occurrence and progression of viral hepatitis infections and autoimmune liver diseases, in addition to systemic lupus erythematosus and pulmonary fibrosis." (PMID 38809509, 2024). "The CNV of FCGR3B has been reported to be associated with susceptibility to a number of autoimmune diseases including systemic lupus erythematosus (SLE), organ-specific autoimmunity, and rheumatoid arthritis." (PMID 25594501, 2015). "The FCGR3B low-copy number duplication has been correlated with renal involvement in a lupus-like model and in humans." (PMID 31557984, 2016). "Our data suggest that these circulating autoantibodies represent a potential connection between low FCGR3B CN and human lupus, especially LN." (PMID 23864940, 2013). "We compared the frequencies of the functional SNPs of FCGR2A (FcγRIIa-H131R, rs1801274), FCGR2B (FcγRIIb-I232T, rs1050501), FCGR3A (FcγRIIIa-V158F, rs396991) and FCGR3B variants (FcγRIIIb NA1 and NA2) between lupus and healthy controls in an indigenous African Caribbean population." (PMID 40728959, 2025). "In particular, single nucleotide polymorphisms (SNPs) in FCGR2A (R131H), FCGR2B (I232T) FCGR3A (V158F) and FCGR3B (NA1/NA2), have been reported in association with systemic lupus erythematosus (SLE), rheumatoid arthritis (RA) and/or idiopathic thrombocytopenia purpura (ITP)." (PMID 20957197, 2010).
systemic lupus erythematosus (continued). "Both FCGR3B CNV and its HNA-1a allotype have been related with the clinical course of autoimmune disease, particularly systemic lupus erythematosus (SLE)." (PMID 34108956, 2021). "FCGR3B, FCGR2A and ITGAM are immune-related genes, all of which are known as biomarkers for systemic lupus erythematosus." (PMID 33602227, 2021). "In support of this notion is the finding that low copy number of FCGR3B (Fc fragment of IgG, low affinity IIIb, receptor (CD16b)), has been coupled to the systemic autoimmune diseases systemic lupus erythematosus (SLE), vasculitis, microscopic polyangiitis and Wegener's granulomatosis." (PMID 21851588, 2011). "FCGR3B CNV has been shown to affect various diseases, i.e., a low CNV of FCGR3B was shown to result in an increased susceptibility to autoimmune diseases like systemic lupus erythematosus (SLE), primary Sjogren's syndrome (pSS), Wegener's granulomatosis (WG) and rheumatoid arthritis (RA)." (PMID 30761158, 2018). "CNVs in FCGR3B, CCL3L1, and C4 for systemic lupus erythematosus (SLE), DEFB4 for Crohn disease, alpha-defensin for Psoriasis, CCL3L1 for susceptibility to HIV-1 infection, the RHD gene for the Rh-negative blood group, and the alpha-globin gene for alpha-thalassemia, have been reported." (PMID 23936009, 2013). "Other studies have reported no FCGR3B CNV associations with Kawasaki disease, antiglomerular basement membrane disease, and Behcet's disease nor with vasculitis complicating systemic lupus erythematosus." (PMID 24027635, 2013).
autoimmune disease (15 papers, 2010 to 2025). A disorder resulting from loss of function or tissue destruction of an organ or multiple organs, arising from humoral or cellular immune responses of the individual to their own tissue constituents. "As a result, FCGR3B has been implicated in various autoimmune diseases, leading to extensive research in this field." (PMID 38809509, 2024). "Recent meta-analyses confirmed the association between FCGR3B copy numbers and susceptibility with autoimmune diseases for low FCGR3B copies for SLE, Sjogren's syndrome and Wegener's granulomatosis." (PMID 31632391, 2019). "Overall, deletions of FCGR3B as part of CNR1 are strongly associated with development of autoimmune diseases." (PMID 31632391, 2019). "Copy number of the genes FCGR3A and FCGR3B has previously been reported to affect susceptibility to several autoimmune diseases and chronic inflammatory conditions." (PMID 25594501, 2015). "If the presence of a low FCGR3B CN increases the susceptibility to RA then the function of this receptor and how a low CN predisposes to the development of autoimmune disease needs to be considered." (PMID 22309893, 2012). "In humans, low copy number of FCGR3B, an orthologue of rat Fcgr3, was associated with glomerulonephritis in the autoimmune disease systemic lupus erythematosus." (PMID 22379396, 2011). "The present study aimed to investigate the presence of copy number variations (CNVs) in the FCGR3B gene and its potential association with the autoimmune disease rheumatoid arthritis (RA)." (PMID 20957197, 2010). "During the preparation of this manuscript, three independent studies report on the FCGR3B gene copy number in association with the risk of developing autoimmune diseases, including RA." (PMID 20957197, 2010). "Similarly, FCGR3B participates in immune responses to infections, with studies indicating altered expression in various infectious and autoimmune diseases, suggesting limited specificity as a diagnostic marker." (PMID 41259376, 2025). "Another study found that copy number variations of FCGR3B were associated with susceptibility to autoimmune diseases, suggesting that FCGR3B may be involved in regulating immune responses." (PMID 37670814, 2023). "FCGR3B is located in chromosomal region 1q21–23, which is associated with autoimmune diseases." (PMID 36553504, 2022). "Furthermore, genomic variants, copy number variations, and single-nucleotide polymorphisms within FCGR3B have been shown to be significantly associated with several autoimmune diseases." (PMID 34458692, 2021). "Associations between deletions of FCGR3B and susceptibility to adult autoimmune diseases have been found for SLE, ulcerative colitis, rheumatoid arthritis (RA), ankylosing spondylitis, systemic sclerosis, primary Sjögren syndrome (SS), microscopic polyangiitis and Wegener's granulomatosis." (PMID 31632391, 2019). "If FCGR3B plays a role in the adherence of neutrophils to immune complexes and their subsequent clearance, then by what mechanism could a reduced CN predispose to autoimmune disease?" (PMID 22309893, 2012). "Given that deletion at FCGR3B is strongly implicated in autoimmune disease etiology the lack of identification of a tag SNP here does not provide an immediate solution for association analysis of FCGR3B CN with disease in most populations." (PMID 23646200, 2013). "In the studies of genetic predisposition to develop autoimmune disorders, CNV was proven only for FCGR2C, FCGR3A and FCGR3B, but not for FCGR2A and FCGR2B genes." (PMID 28472129, 2017).
rheumatoid arthritis (12 papers, 2006 to 2025). A chronic, systemic autoimmune disorder characterized by inflammation in the synovial membranes and articular surfaces. "In this study, we explored the association of the Fc gamma receptor 3B gene (FCGR3B) copy number variation (CNV) with rheumatoid arthritis (RA) susceptibility and related serological traits in the Pakistani population." (PMID 36553504, 2022). "Having 0 or 1 copy of FCGR3B has been associated with SLE and rheumatoid arthritis (RA)." (PMID 40411624, 2025). "At present the relationship between FCGR3B and rheumatoid arthritis (RA) is unclear." (PMID 22309893, 2012).
COVID-19 (7 papers, 2021 to 2025). A disease caused by infection with severe acute respiratory syndrome coronavirus 2. "It will be valuable to investigate whether MoAM cells or FCGR3B gene could be used in adoptive cellular therapies to curb COVID-19-associated symptoms." (PMID 34458692, 2021). "The direct functional role of FCGR3B in dysregulated immunity in general, and COVID-19 specifically remains to be elucidated." (PMID 34458692, 2021). "A cohort of severe COVID-19 patients from Dubai also exhibited a significantly higher fraction of severe patients with upregulated FCGR3B compared with controls." (PMID 34458692, 2021). "Our identification of high FCGR3B expression in severe COVID-19 patients suggest a potential role of the corresponding protein product, FcγRIIIb, in the recruitment and activation of other immune cells to the infection site." (PMID 34458692, 2021). "In the data sets analyzed in our present study, FCGR3B showed severe COVID-19 specific expression that was restricted to a subtype of monocyte-derived macrophages which also showed upregulation of CCL3L1, a known inflammatory marker for MoAMs." (PMID 34458692, 2021). "In silico findings were validated by upregulation of FCGR3B in nasopharyngeal swabs of severe ICU COVID-19 cases, particularly in older patients and those with comorbidities." (PMID 34458692, 2021). "We further validated the expression of FCGR3B in a bulk data set from nasopharyngeal swabs and observed upregulation of FCGR3B in severe COVID-19 samples compared with control (p = 0.004)." (PMID 34458692, 2021). "Upregulation of FCGR3B in severe COVID-19 was validated in datasets from multiple tissue types including single-cell BALF, bulk PBMC and bulk nasopharyngeal data." (PMID 34458692, 2021). "The expression of FCGR3B was then validated in another single-cell BALF data set in which upregulation of FCGR3B in severe COVID-19 samples as compared with control was again evident (p < 1.08 × 10−143)." (PMID 34458692, 2021). "By this approach, we identified the most differentially regulated gene that demarcated cluster 11 in samples from patients with severe COVID-19, namely FCGR3B." (PMID 34458692, 2021). "Interestingly, a single-cell RNA study identified high expression of FCGR3B in alveolar macrophages in severe COVID-19 patients." (PMID 37620910, 2023). "However, conditional FCGR3B expression in CCL3L1 positive isolated cells in the nasopharyngeal swabs would have precisely defined the correlation among MoAM, FCGR3B, and COVID-19 severity." (PMID 34458692, 2021). "In summary, FCGR3B is upregulated in a macrophage subtype (MoAM_CCL3L1) that is only observed in severe COVID-19 cases, hence differential regulation due to comorbidities or genetic mutations that impair FCGR3B are predicted to contribute to the severe course of COVID-19." (PMID 34458692, 2021). "To test whether FCGR3B can be used as a marker for COVID-19 severity, we used clinical samples of severe COVID-19 patients obtained from Dubai Health Authority." (PMID 34458692, 2021). "The integrated, multidimensional approach in our study lays the foundation for understanding the role of the FCGR3B gene positive subtype of MoAM in COVID-19 severity, which may pave the way for novel immune-targeted therapies." (PMID 34458692, 2021). "The expression level per cluster for CCL3L1 and FCGR3B marker in severe, moderate and control single-cell transcriptome data clearly reveals a distinct pattern of FCGR3B and restrictive expression for MoAM (cluster 11) in severe COVID-19 cases." (PMID 34458692, 2021). "Additional lines of evidence from transcriptomic data and in vivo of severe COVID-19 cases suggest that FCGR3B may identify a specific subtype of MoAM in patients with severe COVID-19 that may present a novel biomarker for screening and prognosis, as well as a potential therapeutic target." (PMID 34458692, 2021).
COVID-19 (continued). "Neutrophils, marked by high FCGR3B expression, were significantly elevated in severe COVID-19 cases, particularly among those who did not survive." (PMID 39928675, 2025). "The expression of FCGR3B in monocytes treated with conditioned medium from spike protein stimulated NHBE of obese subjects was significantly higher than in non-obese subjects (p = 0.006), suggesting FCGR3B as a potential modulator of COVID-19 severity in patients with obesity." (PMID 34458692, 2021). "Yet, in contrast to FCGR3B, the expression of TNFAIP6 (indicator of COVID-19 severity) and CCL3L1 (marker for MoAM) is not restricted to one cluster in all three datasets." (PMID 34458692, 2021).